RSPH4A (radial spoke head component 4A)
Description:
Component of the axonemal radial spoke head which plays an important role in ciliary motility. Essential for triplet radial spokes (RS1, RS2 and RS3) head assembly in the motile cilia (By similarity).
Synonyms: RSHL3; dJ412I7.1; FLJ37974; RSPH6B; CILD11
Tractability: Small molecule: a structure with a bound ligand is known. Antibody: its Gene Ontology location is reachable by antibodies, with medium confidence.
Gene: Protein-coding gene on chromosome 6 (116,616,479 to 116,632,985, forward strand). Ensembl gene ENSG00000111834.
Subcellular location: Cytoplasm, cytoskeleton, cilium axoneme; Cell projection, cilium
Subcellular location (Human Protein Atlas): Connecting piece; Flagellar centriole; Annulus
Gene Ontology:
Biological process: axoneme assembly; cilium movement; radial spoke assembly; cilium assembly; cilium movement involved in cell motility
Cellular component: axoneme; 9+2 motile cilium; cilium; motile cilium; radial spoke; radial spoke head; radial spoke head 1; radial spoke head 2; radial spoke head 3
Genetic constraint (gnomAD): Loss-of-function variants: 38 observed, 61.01 expected, observed/expected ratio (o/e) 0.62, 90% interval 0.48 to 0.82. The upper end of that interval is the gene's LOEUF score, 0.82, which puts it in group 3 of 6, group 1 being the genes least tolerant of losing a copy. Missense variants: 710 observed, 827.7 expected, observed/expected ratio (o/e) 0.86, 90% interval 0.81 to 0.91. Synonymous variants: 259 observed, 296.81 expected, observed/expected ratio (o/e) 0.87, 90% interval 0.79 to 0.97.
Gene-disease validity (ClinGen):
ClinGen rates the evidence that RSPH4A causes each of these diseases.
primary ciliary dyskinesia 11 (autosomal recessive): Definitive.
Homologues: Orthologues: chimpanzee RSPH4A (99% identical), macaque RSPH4A (95% identical), pig RSPH4A (81% identical), dog RSPH4A (81% identical), rabbit RSPH4A (79% identical), mouse Rsph4a (73% identical), guinea pig RSPH4A (61% identical), rat Rsph4a (61% identical), tropical clawed frog rsph6a (43% identical), zebrafish rsph4a (41% identical), Drosophila melanogaster Rsph4a (29% identical). Paralogues in human: RSPH6A (50% identical).
Diseases named in the same sentence as RSPH4A in open-access papers:
RSPH4A is named in the same sentence as 21 diseases in open-access papers, as found by Europe PMC text mining. Sharing a sentence is not in itself a finding about the gene and the disease. The quoted sentences say what the papers report.
primary ciliary dyskinesia (9 papers, 2020 to 2025). A rare, genetically heterogeneous, primarily respiratory disorder characterized by chronic upper and lower respiratory tract disease. "According to public databases, RSPH4A (OMIM:612647) variants have been verified to cause primary ciliary dyskinesia." (PMID 38818043, 2024). "Here, we show the role of the primary ciliary dyskinesia causal gene Rsph4a in the mouse motile cilia." (PMID 32203505, 2020). "Pathogenic variants in RSPH4A (radial spoke head component 4A) are associated with primary ciliary dyskinesia (PCD), a rare genetic ciliopathy." (PMID 40428427, 2025). "The radial spoke head protein 4 homolog A (RSPH4A) gene is one of more than 50 genes that cause Primary ciliary dyskinesia (PCD), a rare genetic ciliopathy." (PMID 36768259, 2023). "Using the keywords “primary ciliary dyskinesia,” “immotile-cilia syndrome,” and “RSPH4A gene,” a PubMed literature search was conducted to locate articles published between 2012 and 2025." (PMID 40852414, 2025). "Primary ciliary dyskinesia (PCD) is a rare genetic disorder primarily characterized by respiratory dysfunction; however, our findings suggest it may also be associated with sleep-related disturbances and neuropsychiatric symptoms, particularly in patients with PCD RSPH4A founder mutation." (PMID 40004884, 2025). "Asthenoteratozoospermia in primary ciliary dyskinesia (PCD) related to RSPH4A variants has not been reported." (PMID 35812741, 2022).
Infertility (6 papers, 2022 to 2025). "In the RSPH family, RSPH9 and RSPH4A encoded a generic component of the radial spoke heads of cilia, and mutation of these genes caused central microtubular pair abnormalities and infertility." (PMID 35955660, 2022). "Moreover, we also described the detailed information of two infertile female patients with RSPH4A variants." (PMID 35812741, 2022). "In a previous study, in the Rsph4a knock-out mice, the oviduct cilia showed two types of abnormal motion patterns: anti-clockwise rotation and beating with small amplitude, which may cause the failure of oocyte pickup and led to female mouse infertility." (PMID 35812741, 2022).
bronchiectasis (3 papers, 2021 to 2025). Segmental, irreversible dilation of the bronchial tree resulting in the accumulation of secretions which leads to obstruction. "Case 9 and 10 with compound heterozygous genetic variants for RSPH4A displayed bronchiectasis on HRCT." (PMID 33670432, 2021). "The latest homozygous variant c.1484C>A in the RSPH4A gene was discovered in Japan, resulting in a reduction in ciliary beat frequency and central microtubule defects, which was also associated with chronic respiratory symptoms and bronchiectasis." (PMID 40852414, 2025). "Interestingly, patients with biallelic pathogenic variants in RSPH4A [c.921 + 3_6delAAGT] mutation showed most of the clinical PCD features including neonatal respiratory distress at birth, bronchiectasis, and sinus diseases as the main phenotype." (PMID 33670432, 2021).
Hydrocephalus (2 papers, 2020 to 2023). Hydrocephalus is an active distension of the ventricular system of the brain resulting from inadequate passage of CSF from its point of production within the cerebral ventricles to its point of absorption into the systemic circulation. "The Rsph4a KO mice show hydrocephalus which is a typical phenotype of PCD." (PMID 32203505, 2020). "RSPH1, RSPH4A, and RSPH9 knockout mouse models recapitulated the PCD phenotypes such as hydrocephalus and impaired mucociliary clearance." (PMID 38091523, 2023).
male infertility (2 papers, 2022 to 2025). The inability of the male to effect fertilization of an ovum after a specified period of unprotected intercourse. "In conclusion, our study reported three novel RSPH4A variants and first demonstrated asthenoteratozoospermia related to RSPH4A variants, which revealed the relationship between RSPH4A variants and male infertility." (PMID 35812741, 2022). "Therefore, we have reason to assume that RSPH4A variants cause male infertility." (PMID 35812741, 2022).
membranous nephropathy (1 paper, 2022). "Quantification of the percentage of proximal tubular expressing the MCC marker RSPH4A, in latter biopsies of patients with membranous nephropathy, revealed that 0,4 ± 0.1% of all proximal tubular cells in these biopsies expressed RSPH4A." (PMID 35372336, 2022).
neurofibromatosis type 1 (1 paper, 2025). A clinically heterogeneous, neurocutaneous genetic disorder characterized by cafe-au-lait spots, iris Lisch nodules, axillary and inguinal freckling, and multiple neurofibromas. "A homozygous mutation c.667delA, p.S223Afs*15 in the RSPH4A gene was identified in a case with neurofibromatosis type 1, and typical PCD symptoms were confirmed by TEM." (PMID 40852414, 2025).
ovarian carcinoma (1 paper, 2020). A malignant neoplasm originating from the surface ovarian epithelium. "The intersection of the transcriptome (fold change ≥2) and proteome (fold change ≥1.5) included 83 differentially-expressed (DE) targets between CD83-KD and NC ovarian cancer cells, whereas OV-vs.-NC showed only two DE targets (CD83 and RSPH4A)." (PMID 32823589, 2020).
respiratory infections (1 paper, 2018). "Mutations in members of this gene family (RSPH9 and RSPH4A) are specifically linked to recurrent respiratory infections and male subfertility due to impaired sperm motility." (PMID 29391579, 2018).
situs inversus (1 paper, 2012). A congenital condition in which there is complete right-to-left reversal of the position of the major thoracic and abdominal organs (that is, they are arranged in a mirror image of the normal positioning). "The total number of RSPH4A mutations identified in our study indicates that this gene is involved in PCD pathogenesis in 2.2% of Polish PCD families, or in ∼4% considering only families without situs inversus." (PMID 22448264, 2012).
RSPH4A also shares sentences with these, for which no sentence is quoted: COVID-19 (1 paper); genetic disorder (1); inflammation (1); Neonatal respiratory distress (1); neurofibromatosis (1); otitis media (1); pulmonary disease (1); Respiratory distress (1); respiratory failure (1); rhinosinusitis (1); virus infection (1).